DNASE2B (deoxyribonuclease 2 beta)
Description:
Hydrolyzes DNA under acidic conditions. Does not require divalent cations for activity. Participates in the degradation of nuclear DNA during lens cell differentiation.
Synonyms: DLAD
Tractability: Antibody: UniProt predicts a signal peptide or a membrane-spanning region; its Gene Ontology location is reachable by antibodies, with medium confidence.
Gene: Protein-coding gene on chromosome 1 (84,398,484 to 84,415,018, forward strand). Ensembl gene ENSG00000137976.
Subcellular location: Lysosome
Gene Ontology:
Molecular function: deoxyribonuclease II activity; DNA endonuclease activity
Biological process: apoptotic DNA fragmentation; DNA metabolic process
Cellular component: cytoplasm; extracellular region; lysosome
Genetic constraint (gnomAD): Loss-of-function variants: 43 observed, 45.84 expected, observed/expected ratio (o/e) 0.94, 90% interval 0.73 to 1.21. The upper end of that interval is the gene's LOEUF score, 1.21, which puts it in group 5 of 6, group 1 being the genes least tolerant of losing a copy. Missense variants: 382 observed, 420.01 expected, observed/expected ratio (o/e) 0.91, 90% interval 0.84 to 0.99. Synonymous variants: 152 observed, 156.31 expected, observed/expected ratio (o/e) 0.97, 90% interval 0.85 to 1.11.
Homologues: Orthologues: chimpanzee DNASE2B (99% identical), macaque DNASE2B (98% identical), dog DNASE2B (83% identical), guinea pig DNASE2B (81% identical), mouse Dnase2b (66% identical), rat Dnase2b (65% identical), pig DNASE2B (65% identical), tropical clawed frog dnase2b (51% identical), zebrafish dnase2b (44% identical), Caenorhabditis elegans nuc-1 (30% identical), Caenorhabditis elegans crn-6 (30% identical), Drosophila melanogaster DNaseII (29% identical), and 1 more. Paralogues in human: DNASE2 (35% identical).
Diseases named in the same sentence as DNASE2B in open-access papers:
DNASE2B is named in the same sentence as 8 diseases in open-access papers, as found by Europe PMC text mining. Sharing a sentence is not in itself a finding about the gene and the disease. The quoted sentences say what the papers report.
cataract (3 papers, 2018 to 2025). Partial or complete opacity of the crystalline lens of one or both eyes that decreases visual acuity and eventually results in blindness. "This is of significance because Dnase2b is necessary for fiber cell nuclear degradation during terminal differentiation, and mice deficient for this gene exhibit cataracts." (PMID 29565969, 2018). "Accordingly, Dnase2b KO mice present undifferentiated fiber cells containing condensed undigested DNA leading to the development of cataracts." (PMID 33717156, 2021). "The expression of Dnase2b is regulated by lens-specific heat shock transcription factor 4 (HSF4), the deficiency of which in mice caused cataracts and SNPs in humans were linked to cataractogenesis." (PMID 33717156, 2021). "Mice lacking the DNASE2B gene fail to degrade DNA during lens cell differentiation, leading to the accumulation of undigested DNA in fibroblasts and ultimately resulting in cataracts." (PMID 40493560, 2025).
bladder cancer (1 paper, 2023). "The high expression of ABCB9, SPTBN2, GULP1, IGF1, P4HB, NES and DPYSL2 and the low expression of ANXA6, OAS1, RAD9a, DNASE2B and FANCF would be beneficial to the prognosis of bladder cancer patients." (PMID 37845668, 2023).
myopia (1 paper, 2023). "Additionally, we identified 4 significant DEGs of myopia: KIAA1211, CALR3, DNASE2B, and CCDC178, and 2 common targets: AR and TYRO3 among DZP, myopia, DEG analysis, and WGCNA." (PMID 37747014, 2023).
thyroid cancer (1 paper, 2025). "Collectively, our findings indicate that DNASE2B is highly expressed in thyroid carcinoma and plays a crucial role in the imbalance of proliferation and invasion of thyroid carcinoma cells." (PMID 40493560, 2025). "Western blot assays demonstrated that DNASE2B were significantly upregulated in thyroid carcinoma, while siRNA effectively interfered with DNASE2B expression." (PMID 40493560, 2025).
tumor (2 papers, 2023 to 2025). "There have been reports of endonucleases affecting redox functions in the thyroid, which may provide a clue as to how DNASE2B influences thyroid function and thus tumor prognosis." (PMID 40493560, 2025). "However, there have been no reports linking DNASE2B to tumor-related mechanisms, and only preliminary result suggests an association between DNASE2B and chemotherapy resistance." (PMID 40493560, 2025).
cancer (1 paper, 2018). A tumor composed of atypical neoplastic, often pleomorphic cells that invade other tissues. "In contrast, a small group of cancer-associated genes were up-regulated during overhaul including: Calpain 11 (Capn11), RAR-Related Orphan Receptor Gamma (Rorc), and Deoxyribonuclease II Beta (Dnase2b)." (PMID 30130361, 2018).
DNASE2B also shares sentences with these, for which no sentence is quoted: COVID-19 (1 paper); lung carcinoma (1).